PAX1 (paired box 1)
Diseases named in the same sentence as PAX1 in open-access papers (continued):
Sharing a sentence is not in itself a finding about the gene and the disease.
DiGeorge syndrome (4 papers, 2020 to 2023). "•PAX1 deficiency shares new overlapping features with DiGeorge syndrome, including immunodeficiency and hypoparathyroidism." (PMID 37689091, 2023). "New overlapping features with DiGeorge syndrome included primary hypoparathyroidism (n = 5) and congenital heart defects (n = 2), in line with PAX1 expression during early embryogenesis." (PMID 37689091, 2023).
esophageal cancer (4 papers, 2017 to 2023). A primary or metastatic malignant neoplasm involving the esophagus. "Interestingly, the PAX1 gene has been shown to suppress methylation in ovarian, cervical, oral, head and neck, and esophageal cancers and may act as a tumor suppressor gene." (PMID 37689091, 2023). "However, whether the promoter methylation status of the PAX1 and ZNF582 genes is associated with ESCC and could be novel biomarkers for early esophageal cancer detection remains to be elucidated." (PMID 28241446, 2017). "The methylation of PAX1 and ZNF582 detected in these cells could act as biomarkers for esophageal cancer screening in the future, which could replace traditional endoscopy as an equally effective but less invasive way of diagnosing for esophageal cancer." (PMID 28241446, 2017).
Immunodeficiency (4 papers, 2022 to 2026). Failure of the immune system to protect the body adequately from infection, due to the absence or insufficiency of some component process or substance. "The mechanism involved in immunodeficiency suggests that TT should restore the immune phenotype of PAX1 deficiency." (PMID 37689091, 2023).
lymph node metastasis (4 papers, 2017 to 2023). "A nomogram containing the risk factors for PAX1 methylation status, lymph node metastasis, pathological type and tumor size was further constructed to predict the probability of tumor residual after chemo-radiotherapy (AUC = 0.823, 95% CI 0.736–0.910)." (PMID 37533109, 2023). "According to the univariate binary logistics regression analysis, tumor size (p = 0.000), PAX1 status (p = 0.026), and lymph node metastasis (p = 0.000) were associated with sensitivity to radiotherapy." (PMID 37533109, 2023). "However, there is a tendency that PAX1 methylation level was associated with TNM stage and lymph node metastasis with a p value of 0.068 and 0.073, respectively, while ZNF582 methylation level was associated with carcino-embryonic antigen (CEA) concentration with a p value of 0.076." (PMID 28241446, 2017). "We explored the correlation of baseline PAX1 methylation status with clinical outcomes including age, FIGO stage, pathological type, HPV status, lymph node metastasis, tumor size and short-term efficacy." (PMID 34335930, 2021).
ovarian carcinoma (4 papers, 2019 to 2025). A malignant neoplasm originating from the surface ovarian epithelium. "Among them, PAX1 functions as a tumour suppressor and is known to be epigenetically silenced in several malignancies, including ovarian cancer, oral squamous cell carcinoma and oesophageal squamous cell carcinoma." (PMID 41229153, 2025). "On the contrary, PAX1 was aberrantly methylated, and downregulated, in cervical, oral, and ovarian cancer, suggesting that PAX1 is a tumor suppressor gene." (PMID 31235851, 2019). "In epithelial ovarian cancer (EOC), PAX1 was significantly hypermethylated in HPV16/18‐infected EOC tissues." (PMID 30636379, 2019).
squamous cell carcinoma (4 papers, 2017 to 2025). A carcinoma arising from squamous epithelial cells. "Combined with HPV-16/18 genotyping, both a dual methylation test for PAX1/ZNF582 and testing for ZNF582 methylation demonstrated 100% association of methylation with pathology results, indicating carcinoma in situ or squamous cell carcinoma." (PMID 28977944, 2017). "Furthermore, marker performance varies by histology: PAX1 is more sensitive for squamous cell carcinoma, while JAM3 better detects adenocarcinoma and rare cervical tumors." (PMID 41358249, 2025).
cervical tumor (3 papers, 2015 to 2025). "Combined parallel testing using Pap smears and PAX1 or SOX1 methylation tests may provide better performance than a combination of Pap smears with HPV-testing in detection of cervical neoplasm." (PMID 25985991, 2015). "In this study, we analyzed the concordance and clinical performance of DNA methylation biomarker (PAX1, SOX1, and ZNF582) detection in self-collected vaginal samples and physician-collected cervical samples for the identification of cervical neoplasm." (PMID 25985991, 2015). "The clinical performance of PAX1, SOX1, and ZNF582 as biomarkers of cervical neoplasm has been validated in multi-center clinical trials; therefore, analysis of changes in the methylation status of these genes could be applied for self-collected vaginal samples." (PMID 25985991, 2015).
T-cell deficiency (3 papers, 2022 to 2025). "In addition, biallelic PAX1 (paired box 1) variants underlie OTFCS type 2 with T-cell deficiency (OTFCS2), while loss-of-function (LoF) variants in EYA4 (EYA transcriptional coactivator and phosphatase 4) have more recently been reported in a single affected family." (PMID 41300719, 2025). "In humans, the phenotypic effects of the PAX1 duplication have not been yet described, whereas homozygous mutations of this gene have been associated with otofaciocervical syndrome 2 with T-cell deficiency (OTFCS2) (#615560)." (PMID 35407632, 2022). "Even though the mechanisms of malignant transformation in DGS are not well-known, it may well be that the T cell deficiency and consequent persistent infections, such as EBV, are causally implicated, and this could also apply to the PAX1 deficiency." (PMID 37689091, 2023).
cervical squamous cell carcinoma (2 papers, 2019 to 2025). A squamous cell carcinoma arising from the cervical epithelium. "In addition, hypermethylated PAX1 associated with poor progression-free survival (PFS), and poor overall survival (OS), in patients with cervical squamous cell carcinoma." (PMID 31235851, 2019).
oral squamous cell carcinoma (2 papers, 2017 to 2025). "Previous studies have shown that the methylation status of PAX1 and ZNF582 genes is a useful testing to distinguish tumor and non-tumor tissues in cervical and oral squamous cell carcinoma." (PMID 28241446, 2017).
Thymic aplasia (2 papers, 2022 to 2023). "Beyond thymic aplasia/hypoplasia, we report a clinical overlap between DGS and PAX1 deficiency, including primary hypoparathyroidism and congenital heart defects." (PMID 37689091, 2023).
Autoimmunity (1 paper, 2023). The occurrence of an immune reaction against the organism's own cells or tissues. "In summary, human PAX1 deficiency causes syndromic features and SCID/CID characterized by impaired T cell development and susceptibility to infections, autoimmunity, and malignancy, with variable clinical penetrance of the different features." (PMID 37689091, 2023).
cyst (1 paper, 2019). A sac-like closed membranous structure that may be empty or contain fluid or amorphous material. "Knockdown of mlf gene also led to a decrease in the levels of CWP1, MYB2, WRKY, PAX1, and CDK2 proteins and cwp1-3, myb2, wrky, pax1, and cdk2 gene expression and cyst formation, suggesting a positive role of MLF in inducing cwp1-3, myb2, wrky, pax1 and cdk2 genes and cyst formation." (PMID 30856211, 2019).
degenerative disc disease (1 paper, 2017). "Importantly, identification of Pax1 and Pax9 as regulators of critical IVD genes has implications in understanding certain forms of kyphoscoliosis that have been linked to human PAX1 and PAX9, as well as degenerative disc disease." (PMID 28011632, 2017).
Down syndrome (1 paper, 2023). "Oligodontia is most commonly associated with several syndromes like ectodermal dysplasia, Down syndrome, and Van der Woude syndrome that involve the mutation of the MSX-1 and PAX-1 genes." (PMID 37378140, 2023).
Hyperkeratosis (1 paper, 2024). Hyperkeratosis is a histopathological term defining a thickened stratum corneum and may be present in many different skin conditions, with many possible overlaps. "The gene methylation panel based on ZNF582 and PAX1 yielded a sensitivity ranging from 31% for hyperplasia/hyperkeratosis to 90% for moderate dysplasia oral lesions." (PMID 39138540, 2024).
Hypocalcemia (1 paper, 2023). An abnormally decreased calcium concentration in the blood. "PAX1 deficiency should be considered in patients with syndromic features who suffer from infections, Omenn-like skin disease, chronic diarrhea, or hypocalcemia." (PMID 37689091, 2023). "Syndromic patients with hypocalcemia and cardiac abnormalities should be evaluated for PAX1 deficiency." (PMID 37689091, 2023).
neural tube defect (1 paper, 2022). A congenital defect characterized by failure of the neural tube to close completely; this results in the presence of openings in the brain or spinal cord. "Moreover, a PAX1 missense mutation with changing of Gln to His at position 42 in the paired-box domain (Gln139His) was identified in one patient with spina bifida, a kind of congenital malformation due to the neural tube defect (NTD)." (PMID 36393845, 2022).
Omenn syndrome (1 paper, 2020). An inflammatory condition characterized by erythroderma, desquamation, alopecia, chronic diarrhea, failure to thrive, lymphadenopathy, and hepatosplenomegaly, associated with severe combined immunodeficiency (SCID). "Different biallelic deleterious PAX1 variants cause OTFCS2 and SCID, characterized by absent thymic shadow, chronic diarrhea, recurrent respiratory infections, pneumonia, and also Omenn Syndrome." (PMID 32922396, 2020).
parathyroid neoplasms (1 paper, 2022). "For example, transcription factors, including paired box-1 (PAX1), have an active role in parathyroid neoplasms." (PMID 36532647, 2022).
small cell neuroendocrine carcinoma (1 paper, 2025). "Moreover, small cell neuroendocrine carcinoma exhibits a distinct methylation profile and previous studies have reported negative PAX1 methylation in these tumors." (PMID 41358249, 2025).
Stroke (1 paper, 2022). Sudden impairment of blood flow to a part of the brain due to occlusion or rupture of an artery to the brain. "In our study, 415 mRNAs were found to be associated with the effect of 20(R)-Rg3 on stroke recovery, while the expression of these genes, such as Tagln, Vim, Ptges, Pax1, Cxcl3 and Ccl20, was also significantly altered in our sequencing results." (PMID 35268674, 2022).
cancer (30 papers, 2016 to 2025). A tumor composed of atypical neoplastic, often pleomorphic cells that invade other tissues. "Among these comparisons, PAX1 methylation demonstrated statistically significant diagnostic utility in differentiating carcinoma from NILM, with increased sensitivity and specificity." (PMID 40564169, 2025). "While both PAX1 and HOXA9 (or related HOX genes) have been studied in the context of cancer-related methylation, their presence in the same diagnostic panels does not imply direct functional cooperation between them." (PMID 40699796, 2025). "MAL methylation was highly specific for carcinoma, whereas PAX1 methylation appeared earlier in the disease course, suggesting its potential utility for detecting precancerous changes." (PMID 40564169, 2025). "Regarding PAX1, methylation levels were significantly higher in carcinoma than in NILM (p = 0.003), LSIL (p = 0.003), and HSIL (p = 0.015), while comparisons among the non-carcinoma groups did not yield statistically significant differences." (PMID 40564169, 2025). "Again, the methylation profiles of the RASSF1, CDH1, PAX1, and PTEN phosphatase and tensin homolog (PTEN) tumor suppressor genes were analyzed, and higher plasma values of methylation were found for CDH1 and PAX1 genes in malignant ovarian lesions." (PMID 38275400, 2024). "Many studies have reported the tumor suppressive function of PAX1 in various types of cancers, such as cervical, oral, and esophageal cancers." (PMID 37533109, 2023). "So far, most reports of PAX1 in cancer cells focus in the methylation status of PAX1, limited articles showed further molecular mechanisms in these processes." (PMID 36393845, 2022). "Hypermethylation of PAX1 has been reported as a candidate methylated biomarker for oral dysplasia/cancer detection and used to differentiate normal cervical mucosa from CC specimens." (PMID 34882728, 2021). "Both methylation of ZNF582 and PAX1 were significantly higher at the cancer sites than at the adjacent normal sites." (PMID 34359370, 2021). "Hypermethylated PAX1 is important in cancer progression that functions in regulating cellular differentiation and proliferation." (PMID 32328088, 2020). "Hypermethylated ZNF582 and PAX1 genes have also been found in mouth rise samples applicable to the detection of oral dysplasia and cancer." (PMID 33178175, 2020). "Here, we present the first comprehensive, functional investigation of the mechanistic role of PAX1 in cancer." (PMID 31235851, 2019). "The PAX1(a paired-box transcription factor) gene serves as a crucial tumor suppressor, with aberrant methylation patterns being consistently detected across multiple cancer types." (PMID 40777030, 2025). "Patients exhibiting high methylation in SOX1, PAX1, and ZNF582 exhibited increased risk of cancer." (PMID 40256126, 2025). "Moreover, HR-HPV infection, MTHFR polymorphism, and PAX1 methylation increased the risk of both CIN and cancer." (PMID 40291776, 2025). "The best diagnostic performance for carcinoma was achieved with the combined methylation analysis of CADM1 and MAL (AUC = 0.912), which outperformed the individual markers: CADM1 (AUC = 0.770), MAL (AUC = 0.770), and PAX1 (AUC = 0.813)." (PMID 40564169, 2025). "On the other hand, women with negative PAX1 methylation do not need immediate colposcopy or conization because of there being a relatively low short-term progression risk for cancer." (PMID 36713512, 2022). "Higher DNA methylation levels of PAX1 were observed in most kinds of cancer cells, significantly strengthened the observation that PAX1 often acts as a tumor suppressor." (PMID 36393845, 2022). "Recently, an emerging role of PAX1 in cancers was clarified." (PMID 36393845, 2022). "These suggest that hypermethylation of SOX1 and PAX1 might play an important role in the diagnosis and cancer progression of CAC." (PMID 33376722, 2020). "PAX1 is silenced by methylation in several cancers and is considered a tumor suppressor gene." (PMID 30636379, 2019).
cancer (continued). "Little is known about the functional role of PAX1 in cancer biology." (PMID 30636379, 2019). "As a tumor suppressor gene, PAX1 may be involved in carcinogenesis and tumor progression to invasive or aggressive cancers." (PMID 28241446, 2017). "For PAX1 methylation studies specifically, multi-center trials with diverse populations(different regions and ethnic groups were included) are indeed needed to establish broader clinical utility, as suggested in the literature on cancer biomarkers and molecular diagnostics." (PMID 40777030, 2025). "Given its roles in the development of multiple tissues, PAX1 might regulate cell proliferation and differentiation of specific cancer cells and thus contributes to the activation or suppression of cancer development in specific tissue contexts when being dysregulated." (PMID 36393845, 2022). "Therefore, PAX1 methylation level not only can provide biomarkers for early detection and diagnosis in cancer patients, but also could predict and monitor early therapeutic response." (PMID 36393845, 2022). "Thus, hypermethylation of PAX1 promoter silences its expression and promotes cancer progression." (PMID 34335930, 2021). "Using the methylation status of PAX1 to determine the cancerous nature (and CIN1–3) of samples from Shanghai, China is associated with a sensitivity and specificity of 81 and 93%, respectively; however, the sensitivity and specificity for cancer versus CIN2/3 is 32% and 90%, respectively." (PMID 32328088, 2020). "Therefore, hypermethylated PAX1 may derepress the oncogenic kinase cascade, thus promoting cancer progression." (PMID 31235851, 2019). "Taken together, this study reveals, for the first time, the functional relevance of PAX1 in cancer biology, and further supports the prospect of targeting multifold oncogenic kinase cascades, which jointly contribute to multiresistance, via epigenetic reactivation of PAX1." (PMID 31235851, 2019). "ROC curve analyses further confirmed the superior performance of the combined CADM1/MAL methylation panel in detecting carcinoma (AUC = 0.912), compared to CADM1 and MAL alone (both AUC = 0.770) and PAX1 (AUC = 0.813)." (PMID 40564169, 2025). "PAX1 activated a group of phosphatases, including DUSP1, 5, and 6, and inhibited EGF/MAPK signaling to suppress cancer development." (PMID 39304838, 2024). "However, the function of PAX1 in cancer biology remains largely unknown." (PMID 31235851, 2019). "The comparison of tissue samples shows the increasing methylation trend from the control sample group to cancer samples in the RASSF1, CDH1 and PAX1 genes." (PMID 31450846, 2019). "The sensitivities and specificities of PAX1 and ZNF582 methylation for the detection of cancer were 100% and 85.7%, and 78.6% and 100%, respectively." (PMID 28241446, 2017). "The methylation levels of PAX1, SOX1, and ZNF582 showed significant elevation in cancer patients." (PMID 40256126, 2025). "Detection of PAX1‐methylation levels in oral scrapings or oral swabs indicated that PAX1‐methylation levels and positive rates increased along with disease severity (SCC > precancerous lesions > normal oral mucosa), but decreased following cancer excision." (PMID 30636379, 2019). "Therefore, PAX1/JAM3 methylation detection could not only reduce the number of patients who were missed or misdiagnosed by cytology, but also offers a highly sensitive marker panel for cancer, especially those unrelated to HPV infection." (PMID 39659794, 2024).